CCL11 (C-C motif chemokine ligand 11)
Diseases named in the same sentence as CCL11 in open-access papers (continued):
Sharing a sentence is not in itself a finding about the gene and the disease.
ischemic stroke (5 papers, 2012 to 2024). A stroke disorder caused by obstruction of blood flow to the brain, due to thrombotic (local blood clot formation) or embolic (due to a blood clot or other material traveling from another site) event. "In the non-hypertensive group, CCL11 rs3744508, LTC4S rs730012, FCER1B rs569108, TGFB1 rs1800469, LTA rs909253 and CCL11 rs4795895 were associated with ischemic stroke." (PMID 22769019, 2012). "Our study demonstrated CCL11 rs4795895 is associated with ischemic stroke after adjusting for multiple testing." (PMID 22769019, 2012). "We found two single nucleotide polymorphisms (SNPs) in CCL11 were associated with ischemic stroke." (PMID 22769019, 2012). "Two SNPs in CCL11 were associated with ischemic stroke (P <0.05) in total study population." (PMID 22769019, 2012). "Ours is the first study to report any association with SNPs of CCL11 and ischemic stroke." (PMID 22769019, 2012). "Initial analysis showed that CCL11 rs4795895 and CCL11 rs3744508 were significantly associated with ischemic stroke by adjusting for age, sex, BMI and hypertension status, and after adjusting for multiple testing by FDR, CCL11 rs4795895 remained significantly associated with ischemic stroke." (PMID 22769019, 2012). "The risk of ischemic stroke can be influenced by genetic variation in the inflammatory agents, including Interleukin-33 (IL-33), interleukin 4 (IL-4), interleukin 6 (IL-6), intercellular adhesion molecule 1 (ICA M-1), E-selectin (E-sel), chemokine (C-C motif) ligand 11 (CCL11), lymphotoxin (LTA)." (PMID 24107076, 2013). "We found that the change in gene expression of CCR3 and ligands (CCL5, CCL11, and CCL24) is positively correlated with infarct volume in our transient rat model of ischemic stroke." (PMID 38332938, 2024). "We measured the change in expression of CCR3 and its ligands (CCL5, CCL11, and CCL24) in the venous blood prior to and after occlusion in our transient rat model of ischemic stroke." (PMID 38332938, 2024). "Ischemic stroke induces the release of different chemokines such as CCL-2, CCL-3, CCL-4, CCL7, CCL-11, CXCL-1, CXCL10, from the ischemic tissue." (PMID 30584250, 2018).
liver diseases (5 papers, 2012 to 2025). "Despite these insights, comprehensive clinical data regarding CCL11 expression patterns across various liver diseases remain limited, highlighting the need for further systematic investigation." (PMID 40429807, 2025). "The dual role of CCL11 in both injury response and regeneration provides critical insights into liver pathophysiology and liver diseases." (PMID 40429807, 2025). "While few studies have investigated the role of CCL11 in liver diseases, eotaxin gene expression has been shown to be up-regulated in senescent compared to proliferative HSCs." (PMID 36358697, 2022). "Several studies have shown that CCL-11 is involved in the pathogenesis of inflammatory processes during liver diseases as well." (PMID 22966239, 2012). "These chemokines such as CCL2, CCL7, CCL8, CCL11 and CCL12 were demonstrated as pro-fibrosis cytokines in liver diseases and highly expressed during our murine schistosomiasis model, and reduced more or less after PZQ treatment." (PMID 22905138, 2012). "In addition, the pathogenic role of other chemokines such as CCL2 (MCP-1), CCL17, CCL11, CCL20 and CXCL1 in liver diseases remains unclear and requires further investigation." (PMID 32641985, 2020).
mood disorder (5 papers, 2016 to 2022). A cognitive disorder a disturbance in which the person's mood is hypothesized to be the main underlying feature. "In humans, we found that the CCL11 expression was significantly affected by lifetime mental disorders, especially mood disorders and anxiety disorders." (PMID 28149283, 2016). "However, when this balance is disturbed in age-related cognitive impairments and/or mood disorders, similar immune changes are observed: for example, elevated CCL-11 plasma levels in schizophrenic patients." (PMID 36362993, 2022). "Some patients with mood disorders and premenstrual syndrome show increased plasma CCL-11 levels." (PMID 32887304, 2020). "Thus, while changes in CCL11 are observed in women with recurrent MDD with suicidal ideation and in young adults with mood disorders, another study in elderly patients with MDD showed no changes." (PMID 30870525, 2019).
Myocardial fibrosis (5 papers, 2016 to 2021). "It has been reported that eotaxin-1/CCL11 levels were correlated with myocardial fibrosis and mast cell density." (PMID 32147601, 2020). "They suggested that targeting eotaxin/CCL11 with monoclonal antibodies could reduce cardiac mast cell infiltration, possibly resulting in decreased myocardial fibrosis and improved contractile function after heart transplantation." (PMID 33871784, 2021). "Our microarray and quantitative PCR assays also showed that T. cruzi significantly upregulated transcript levels of chemokines like CCL-11 previously shown to correlate with myocardial fibrosis and inflammatory cytokines that play a role in the pathogenesis of fibrosis." (PMID 26771187, 2016). "CCL11 bind CCR3 to stimulates the migration of immune cells like neutrophils and was shown to recruit such cells to the heart and contribute to myocardial fibrosis." (PMID 32923679, 2020).
Arthritis (4 papers, 2011 to 2025). Inflammation of a joint. "In an equine IL-1β-induced carpal synovitis model, CCL2, CCL3, CCL5, and CCL11 were identified as sensitive biomarkers during the early stages of joint inflammation (synovitis), exhibiting temporal variations in their response." (PMID 40496923, 2025). "We guess the serum CCL11 level is affected by some factors other than arthritis." (PMID 33846499, 2021). "Our data suggest that synovial fluid lubricin, in addition to a panel of synovial fluid biomarkers, including TNF-α, CCL2, CCL11 and sGAG, may have potential for elucidating the progression of early joint inflammation." (PMID 33980227, 2021). "Both IL-1β-induced synovitis and intra-articular lavage resulted in transient joint inflammation with elevations in synovial fluid TP, WBC count, and PGE2; however, increases in TNF-α and inflammatory chemokines CCL2, CCL3, CCL5, and CCL11 were predominantly restricted to synovitis joints only." (PMID 33980227, 2021).
gastric cancer (4 papers, 2015 to 2020). A primary or metastatic malignant neoplasm involving the stomach. "The circulating eotaxin-1/CCL11 level has been used as a biomarker of gastric cancer and postmenopausal osteoporosis in clinical trials." (PMID 32147601, 2020).
glioblastoma (4 papers, 2016 to 2025). The most malignant astrocytic tumor (WHO grade IV). "The first experiment evaluated the chemoattraction potential of the chemoattractants CXCL10, CCL2, CCL11 individually and in combination on two established glioblastoma cell lines: F98 and U87MG." (PMID 34830041, 2021). "In the present study, we surveyed and demonstrated the potency of the chemokines CXCL10, CCL2 and CCL11 to attract neoplastic glioblastoma cells in vitro and in vivo." (PMID 34830041, 2021). "Tian et.al (2016) showed that CCR3, was overexpressed and that CCL11/CCR3 signaling promoted the proliferation, migration and invasion of glioblastoma cells." (PMID 40484866, 2025).
heart failure (4 papers, 2016 to 2022). Inability of the heart to pump blood at an adequate rate to meet tissue metabolic requirements. "Metformin has also been found to suppress plasma cytokines—including the aging-associated cytokine, C–C motif chemokine ligand 11 (CCL11)—in patients with heart failure who do not have T2DM." (PMID 31526382, 2019). "Concentrations of MCP-1/CCL-2, EOTAXIN/CCL11 and RANTES/CCL5 were significantly higher in the saliva of heart failure subjects with both NS and HS compared to the controls, while IL-8/CXCL8 level was considerably higher only in heart failure patients with NS." (PMID 36300113, 2022). "In further work, we find that anti-inflammatory effects of metformin are exerted irrespective of diabetes status, including suppression of the ageing-related cytokine CCL11 in a nondiabetic heart failure cohort." (PMID 27418629, 2016). "Following up these findings in a double-blind placebo controlled trial in nondiabetic heart failure (trial registration: NCT00473876), metformin suppressed plasma cytokines including the aging-associated cytokine CCL11 (C-C motif chemokine ligand 11)." (PMID 27418629, 2016).
Hepatic steatosis (4 papers, 2022 to 2025). Steatosis is a term used to denote lipid accumulation within hepatocytes. "CCL11-mediated hepatic eosinophilic infiltration and activation results in hepatic steatosis and fibrosis." (PMID 38251375, 2024). "A differential expression of IL-13, G-CSF, CCL11, IL-6 and IL-4 among patients at different stages of hepatic steatosis, highlighted a possible role of an inflammatory response in the development of hepatic steatosis and fibrosis in CHB patients." (PMID 36544761, 2022). "Their findings reveal that the CCL11/CCR3 axis drives macrophage-mediated inflammation and hepatic steatosis, while the genetic ablation of CCL11 or a pharmacological CCR3 blockade significantly attenuates ALD progression." (PMID 40429807, 2025). "IL-13 facilitates hepatic steatosis and fibrosis, the latter through mechanisms including the stimulation of TGF-β1 gene expression and through activation of the JAK-STAT-6 pathway, in turn results in the production of CCL11, an eosinophil chemotactic protein." (PMID 38251375, 2024).
malaria (4 papers, 2020 to 2023). Malaria is a serious and sometimes fatal disease caused by a parasite that commonly infects a certain type of mosquito which feeds on humans. "Increased TNF, IFN-γ, IL-1, IL-2, IL-6, IL-10, TGF-β, CCL2, CCL3, and G-CSF levels and decreased IL-5, IL-12, IL-17, and CCL11 levels were observed in malaria monoinfection compared to intestinal parasite monoinfection." (PMID 36716305, 2023). "CCL11, a chemokine largely neglected in the field of malaria, emerges as an important marker of exposure or mediator in this condition." (PMID 32365058, 2020). "CCL11, a chemokine poorly studied in the context of malaria, was the only biomarker among the 31 studied to show a negative association (OR<1) with Pv infection, although the associations were lost when stratifying by infection density." (PMID 32365058, 2020). "We had previously shown that non-pregnant women heavily exposed to malaria had lower levels of circulating CCL11 than malaria-naïve controls." (PMID 32365058, 2020). "In a previous study, pregnancy and malaria exposure were associated with decreased plasma concentrations of the chemokine eotaxin-1 (CCL11), and its levels showed the highest (negative) correlation among thirty biomarkers with atypical MBC frequencies in a cohort from Papua New Guinea." (PMID 36380370, 2022). "However, this may not be considered as a bias in the CCL11 analysis, as helminths would actually provoke an increase in CCL11 while we observe a decrease in this chemokine associated to malaria." (PMID 32365058, 2020). "However, for the malaria group, four distinct correlation patterns were observed; first pattern (CCL4, CCL2, CCL3, IL12 and IL2), second pattern (IL-17A, IL-1β, CCL11, IL4), third pattern (IL5, IL7, IL13), and fourth pattern (IL1RA, CXCL10, TNFα, IL2R, CXCL9, IL6)." (PMID 35811678, 2022).
pancreatic cancer (4 papers, 2013 to 2024). "Sherman and colleagues show that ATX suppresses the accumulation of eosinophils in the tumor microenvironment of pancreatic cancer via suppression of CCL11 expression and find that ATX inhibition increases eosinophil influx, promoting tumor cell death." (PMID 38195933, 2024). "Among the cytokines and growth factor assessed, several growth factors and cytokines including IL-6, IL-8, CCL11, and IP-10 are higher in patients with pancreatic cancer." (PMID 24970174, 2013).
psoriasis (4 papers, 2017 to 2025). An autoimmune condition characterized by red, well-delineated plaques with silvery scales that are usually on the extensor surfaces and scalp. "Based on our results, we suggest that the +67 G/A CCL11 polymorphism should be considered as a gene modulator of psoriasis in specific subgroups of patients." (PMID 40149440, 2025). "No similar study analyzing the associations of CCL11 gene variability with psoriasis and some phenotypes of comorbidities was observed by us in the literature." (PMID 40149440, 2025). "Interestingly, when the potential therapeutic target for psoriasis and psoriatic arthritis (PsA) was analyzed via priority index calculation (based on GWAS), CCL11 was identified as a target for PsA therapy." (PMID 40149440, 2025).
ZIKV infection (4 papers, 2018 to 2021). "Increased serum concentrations of both CXCL (CXCL8 and CXCL10) and CCL chemokines (CCL2, CCL3, CCL4, CCL5, and CCL11) were found in acute ZIKV infection." (PMID 29768624, 2018). "ZIKV infection increases the levels of a series of cytokines (IL-1α, IL-6, IL-9, IL-10, IL-12p70, and IFN-γ) and chemokines (CCL2, CCL3, CCL4, CCL5, CCL11, and CXCL1) in mouse brain." (PMID 34399779, 2021).
age-related macular degeneration (3 papers, 2014 to 2020). Age-related loss of vision in the central portion of the retina (macula), secondary to retinal degeneration. "Elevated CCL11 serum concentrations are associated with different stages of age-related macular degeneration (AMD), except for neovascular AMD." (PMID 32489700, 2020). "Dysregulation of the CCR3/CCL11 pathway has been implicated in the pathogenesis of choroidal neovascularisation, a common feature of late age-related macular degeneration (AMD)." (PMID 24575855, 2014).
anaphylaxis (3 papers, 2017 to 2020). An acute hypersensitivity reaction that occurs from exposure to an allergen. "Our results are consistent with those of a recent study that demonstrated no changes in CCL11 or IL-3 levels during anaphylaxis." (PMID 28342911, 2017). "This suggests that this is an unbiased comparison, including the confirmation that the chemokines CCL5 and CCL11, which may affect other important effector cells of allergic inflammation such as eosinophils, are not induced during anaphylaxis." (PMID 33317619, 2020). "The mechanism of anaphylaxis-related basophil migration appears to be selective because no significant changes were seen for lymphocytes, PMNs, or chemotactic factors that might affect other effector cells, such as eosinophils (eg, CCL5 and CCL11)." (PMID 28342911, 2017). "A recent study demonstrated an increase in CCL2 (C-C Motif Chemokine Ligand 2) levels during human anaphylaxis, with no changes demonstrated for the chemokines CCL5 and CCL11." (PMID 33317619, 2020).
Brain Tumors (3 papers, 2021 to 2025). "ROC analysis of immunological molecules in serum and CSF showed that the expression levels of IL-4, IFN-α, IFN-γ, IL-6, TNF-α, CCL4, CCL11, and VEGF exhibited high sensitivity and specificity in distinguishing between brain inflammation and brain tumor groups (p < 0.05)." (PMID 39364412, 2024).
chronic obstructive pulmonary disease (3 papers, 2022 to 2025). A chronic and progressive lung disorder characterized by the loss of elasticity of the bronchial tree and the air sacs, destruction of the air sacs wall, thickening of the bronchial wall, and mucous accumulation in the bronchial tree. "Increased serum levels of CCL11 have been widelydetected in multiple diseases with chronic inflammation of the airways, such asasthma and chronic obstructive pulmonary disease (COPD).Additionally, growing evidence suggests an association between elevated CCL11 andgastrointestinal inflammation." (PMID 40026499, 2025).
colon cancer (3 papers, 2007 to 2022). "Patients with anastomotic leakage could have an upregulated inflammatory response before surgery, as expressed by elevated serological levels of CXCL6 and CCL11 for rectal cancer and hs-CRP levels in patients with colonic cancer respectively." (PMID 35652588, 2022).
emphysema (3 papers, 2009 to 2023). "The levels of inflammatory cytokines related to type 2 inflammation (including CCL11, CCL17, and CCL22) were significantly elevated in the emphysema model compared to the controls." (PMID 37816708, 2023).
encephalitis (3 papers, 2016 to 2025). An acute inflammatory process affecting the brain parenchyma. "The association of MCI in rural-dwelling older adults with the exposure to pesticides, history of encephalitis, meningitis and head trauma, may be in part mediated by CCL11, which is a negative regulator of neurogenesis." (PMID 35885866, 2022). "Significantly higher levels of CCL11 (p = 0.0107), CCL2 (p = 0.0182), CCL5 (p = 0.0171) and CXCL5 (p = 0.0049) were observed in encephalitis patients." (PMID 40517242, 2025). "IL-4 CCL11, CCL17, CCL21), Th17 (IL-17A, GM-CSF), B cell molecules (BAFF, APRIL) and other cytokine/chemokines including IL-21, IL-1b, IL-12p40, CCL2 and IL-12p70 were detected in less than 50% of patients with encephalitis." (PMID 27575749, 2016). "Additionally, marked elevation of several immune markers (CCL11, CCL2, CCL5, CXCL5, and IL-12p70) in the CSF of encephalitis patients may explain the more severe course of infection and poorer outcomes observed (highest number of neurological symptoms and ICU admissions)." (PMID 40517242, 2025).
eosinophilic esophagitis (3 papers, 2016 to 2025). Eosinophilic esophagitis (EoE) is a chronic, allergic disease of the esophagus characterized clinically by symptoms of esophageal dysfunction (including vomiting, dysphagia, feeding disorders, food impaction and abdominal pain) which persist after treatment with proton pump inhibitors (PPIs). "Besides, IL-13 has been implicated in inflammation and remodeling by inducing chemokines (CCL-3, CCL-4, CCL-5 and CXCL-1), and IL-13 is a direct inducer of both CCL11 and CCL24 in eosinophilic esophagitis." (PMID 27533463, 2016).
epilepsy (3 papers, 2022 to 2025). A brain disorder characterized by episodes of abnormally increased neuronal discharge resulting in transient episodes of sensory or motor neurological dysfunction, or psychic dysfunction. "Some chemokine receptors, such as CCL3 and CCL11, are highly expressed in the hippocampus and are associated with epilepsy because they may promote the release of excitatory neurotransmitters." (PMID 37470000, 2023). "The median (IQR) serum CCL11 levels were 118.0 mg/dL in the drug-resistant group and 66.4 pg/dL in the controlled epilepsy group." (PMID 36291442, 2022). "Comparing our two epilepsy groups, we found higher concentrations of CCL11 in the group of drug-resistant patients compared to the controlled epilepsy group." (PMID 36291442, 2022). "We measured the serum interictal quantitative levels of chemokines (CCL2, CCL4, CCL11) and PGE2 in correlation with the seizure frequency and severity in controlled and intractable childhood epilepsies." (PMID 36291442, 2022). "We found that increased CCL11 and PGE2 levels in our patients were correlated with their seizure frequency and epilepsy severity." (PMID 36291442, 2022).
helminth infections (3 papers, 2020 to 2025). "Of particular interest to the topic of cerebral cytokine production action is the finding that helminth infection can result in increased CSF CCL-11/eotaxin concentrations." (PMID 35215252, 2022). "Our observation of elevated Ccl11 in Nb-infected FGT tissues aligns with previous reports of eosinophil accumulation in the murine FGT post-Nb infection, and mirrors established gastrointestinal responses to helminth infections." (PMID 40872306, 2025).
Hodgkins lymphoma (3 papers, 2018 to 2025). A heterogeneous group of malignant lymphoid neoplasms of B-cell origin characterized histologically by the presence of Hodgkin and Reed-Sternberg (HRS) cells in the vast majority of cases. "CCL11 expression is significantly higher in Hodgkin lymphoma tissue." (PMID 30142953, 2018).